IFNG (interferon gamma)
Diseases named in the same sentence as IFNG in open-access papers (continued):
Sharing a sentence is not in itself a finding about the gene and the disease.
infection (continued). "Interferon-gamma (IFN-γ) is a powerful transactivating signal eliciting hundreds of IFN-stimulated genes (ISGs) in humans to help combat infection." (PMID 42296994, 2026). "Cytokine profiling revealed an acute Th1-skewed response, with elevations in CXCL9, CXCL10, IL-27, IFNγ, IL-12, and IL-18 during early infection." (PMID 41636514, 2026). "This treatment limits the recruitment of circulating monocytes to the colon and suppresses IFNγ production by ILCs and T cells in response to infection." (PMID 40614970, 2025). "Class II-restricted CD4+ T cells and interferon-gamma (IFN-γ) are necessary but insufficient to prevent infection or disease." (PMID 40442144, 2025). "We also observed a complete failure of BM progenitor cell populations to respond to infection together with elevated CD4+ T cell IFNγ production." (PMID 41296814, 2025). "RNA seq analysis of infected olfactory bulbs showed that IFNγ was upregulated in the OB while IFN-β was barely detectable at 5 days post-infection." (PMID 39803452, 2025). "During controlled infection, LeishVet stages 1 and 2, a type 1 immune response dominated by interferon gamma (IFN-γ)-secreting CD4 T cells contributes to maintaining low parasite burden (5, –, 7)." (PMID 40741972, 2025). "By evaluating the early infection site following challenge at this time point, we found that a greater abundance of NK cell populations and proinflammatory signaling, including IFNγ, were strongly correlated with protection." (PMID 40478914, 2025). "Lastly, a negative connection with time to culture conversion and a direct correlation between IFNγ and TNFα levels and bacterial burdens, indicating that type 1 cytokines in TB are primarily influenced by infection density." (PMID 40507146, 2025). "In the third infection, IFNγ and IL-21 were once again significantly upregulated at T6 together with TH1-associated chemokine receptors." (PMID 40214640, 2025). "Infection with RHΔompdcΔup induced high IFNγ levels, and these were significantly diminished by a BTN3A1-blocking antibody but not by an IgG1 isotype control." (PMID 40667022, 2025). "As the primary interface between the host and bacterial pathogen, proteomic analysis on colonic IEC identified infection-induced increases in proteins regulated by IFNγ such as NOS2, RegIIIγ, and major histocompatibility complex II (MHCII)." (PMID 39937862, 2025). "Vaccines based on PFR2/3 induced IgG2a response; however, only PFR2 conjugated with HSP70 induced IL12 and IFNγ expression and a degree of protection from Tc infection." (PMID 40005501, 2025). "PEP-R619W mice also had higher concentrations of IFNγ and enhanced IFNγ production by mature NK cells in the liver at 3 days post-infection." (PMID 40791464, 2025). "Interferon gamma (IFN-γ) from immune cells infiltrated at the site of infection plays a key role in the epithelial cell-intrinsic defense." (PMID 40982010, 2025). "We also found weak evidence for a slight increase in CCL20 during infection (median fold change of 1.12 [95% CrI from 0.93 to 1.37]) and a slight decrease in IFNγ (median fold change of 0.85 [95% CrI from 0.55 to 1.24])." (PMID 39836629, 2025). "Anticytokine autoantibodies (AAbs), particularly anti-interferon-gamma (anti-IFN-γ) AAbs, disrupt cytokine functions, leading to infections, autoimmune-like diseases, and conditions resembling interleukin-12 (IL-12)/IFN-γ pathway defects." (PMID 40711078, 2025). "Since both CD4 + and CD8 + T cells induce IFNγ+ during C. auris primary infection, we examined the contribution of CD8 + T cells in regulating C. auris during reinfection." (PMID 40294061, 2025). "The addition of recombinant IFN-γ to BMDMs restricts virus replication, and thus the requirement for IFNγ for JHMV replication during i.n. infection is likely due to the impact of IFN-γ on other cells in the brain." (PMID 39803452, 2025).
infection (continued). "We then primed the transfected cells with IFNγ overnight, infected the cells with B. thailandensis, and quantified the percentage of bacteria forming actin tails at 8 hours post infection (hpi)." (PMID 40196472, 2025). "More specifically, studies in mice show that pulmonary Mab infection drives the activation of T-helper 1 (Th1) cells that are characterized by the simultaneous production of both IFNγ and TNF." (PMID 40415550, 2025). "In general, we recommend avoiding IFNγ while treating infection in CGD to allow better monitoring of fever and laboratory trends." (PMID 41608118, 2025). "We found that 2.5 mg/kg M3 treatment greatly reduced proinflammatory cytokine (IL6, IFNγ, TNFα, and IL-1β) mRNA expression in the lung 3 days after infection, which explains the high efficacy of M3 in protecting mice from lethal IAV infection." (PMID 39601535, 2025). "By 6 weeks post-infection (w58), most infected cattle are detected by the Enferplex (90%) and IFNG (80%) tests, while ~40% are detected using IDEXX." (PMID 40573909, 2025). "IFNγ expression in subcutaneous infection was significantly increased in B cells only, while intravenously infected animals demonstrated elevated IFNγ levels in B cells, T cells, ILCs, and macrophages." (PMID 40178612, 2025). "By incorporating a graphene–Nafion composite film, the biosensor minimizes nonspecific adsorption with a limit of detection (LOD) as low as 740 fM in undiluted human sweat for biomarkers such as interferon-gamma, a key indicator of inflammation and infection." (PMID 40808103, 2025). "In the kidneys of immunocompetent Acanthamoeba sp.-infected mice, IFNγ and TNFα were increased only at the beginning of infection, while in the immunosuppressed mice, those cytokines were increased throughout the entire period of infection." (PMID 40586570, 2025). "A previous study reported that C. trachomatis induced IFNγ+ILC3s in the genital tract to inhibit its own infection in the endometrial tissue." (PMID 40407332, 2025). "Since PEP-R619W NK cells mediate viral titer at early days post-infection and are a key source of IFNγ, we next wanted to determine if they were necessary for mediating weight loss and survival during MHV A59 infection." (PMID 40791464, 2025). "After 4T1 cell infection with SFV delivering inflammatory cytokine gene (SFV/IFNγ and SFV/TNFα), the 4T1 cells produced 2.4 μg/mL IFNγ and 23.6 ng/mL TNFα, respectively." (PMID 40547518, 2025). "This study provides the first evidence that horses naturally infected with WNV develop robust and durable virus-specific T-cell responses, as detected by ex vivo IFNγ ELISpot assay up to one year post infection." (PMID 40867680, 2025). "Research has found that children suffering from AR often produce insufficient amounts of interferon-gamma (IFN-γ), a key antiviral cytokine, potentially explaining their higher rates of infection." (PMID 40564746, 2025). "At 24 h post infection (hpi), ΔGRA12 parasites were consistently cleared more than parental strains in IFNγ-primed conditions, which was rescued in the GRA12-complemented line." (PMID 40240328, 2025). "Various cell signaling cytokines such as tumor necrosis factor-alpha (TNF-alpha), interferon-gamma (IFN-gamma), interleukin-6 (IL-6), and interleukin-10 (IL-10) are activated during infection, facilitating immune cell differentiation." (PMID 40086236, 2025). "In another study, 15-mer peptides with 11-amino-acid overlaps were used to stimulate PBMCs from previously infected individuals; most subjects exhibited low-frequency IFNγ responses approximately four months after infection." (PMID 40867680, 2025). "We noted that infection in female TLR7ko mice boosted IFNG, CCL2, CCL3, and CCL5 expression, although significantly less compared to the female WT group, but these responses were completely blunted in TLR7ko male mice." (PMID 40143355, 2025).
infection (continued). "Here, we show that the increased expression of IFNγ and IL-17A coincides with the formation of immature granulomas during the intermediate phase of the infection." (PMID 39807873, 2025). "The interferon-gamma release assay (IGRA) is capable of identifying Toxoplasma gondii infection as early as four days post-infection (dpi)." (PMID 40559746, 2025). "Gene expression of pro-inflammatory cytokines IL-1β, IL-2, IL-4, and IL-6, as well as IFNγ was significantly upregulated in nasal turbinates in response to infection with all VOCs, compared to mock-infected hamster tissues." (PMID 40295859, 2025). "This is in line with published TnSeq screens, defining rv3041c as a virulence gene in C57BL/6, IFNγ knockout, and collaborative cross 001 and 027 mouse strains, as well as required for growth under hypoxic condition, mimicking an infection setting." (PMID 40911634, 2025). "Key effector mechanisms controlling parasite replication in the early phase of infection include macrophage activation, T cell activation, B cells for antibody production and IFNγ production." (PMID 40746561, 2025). "Specifically, response to “interferon-gamma” and “interferon-beta” were enriched during the early stages of infection (2 hpi, 2 dpi, and 4 dpi)." (PMID 40124358, 2025). "To assess infection-driven inflammation, we analyzed the levels of IL-6 and IFNγ cytokines, which are involved in inflammation and immune activation, and the chemokines IP-10, MCP-1, and MIP-1β, which are primarily involved in the recruitment of immune cells." (PMID 40272151, 2025). "The number of activated T cells (subset 2) increased substantially after infection with upregulation of the IFNG, STAT3, STAT4, IL9, FOXP3, and TGFBR1, TGFBR2 genes." (PMID 40573402, 2025). "Infection of the strain B10.O20 resulted in 15-350× increase of splenocytes’ production of IFNγ IL-2, IL-4, IL-6, IL-10 and IL-17." (PMID 41164189, 2025). "We analyzed levels of cytokines at the site of infection including IFNγ, IL-10, IL-17, IL-4, and IL-13 by quantitative real-time PCR." (PMID 40655011, 2025). "A vaccine consisting of the H99 strain of C. neoformans recombinantly engineered to express murine IFNγ is highly protective in murine infection models." (PMID 41440711, 2025). "Generally, the host immune system mounts a strong interferon-gamma (IFN-γ)-dependent response which effectively controls the rapidly replicating tachyzoite stage during the acute phase of infection." (PMID 40166190, 2025). "The lower IL-4 responses compared to IFNγ further confirm a predominantly Th1-skewed immune response induced by vaccination, consistent with the profile observed during self-limiting natural infection and previous HEV239 findings." (PMID 40733519, 2025). "Induction of gbp by interferon gamma helps to create a chronic form of infection by regulating inflammation following T. gondii infection." (PMID 40855457, 2025). "Infection of Col1a1-K18-hACE2 KI mice induced high levels of IFNγ, IL-6, IP-10, MCP-1, and MIP-1β cytokines." (PMID 40272151, 2025). "Efficacy was demonstrated in the Cryptosporidium parvum IFNγ-KO mouse infection and calf diarrhea models." (PMID 40737275, 2025). "The IL-2/IFNγ T-cell responses to FCoV1 RBD post-first vaccination were negative for HOK, but extremely high for HOL, most likely caused by active infection and vaccine stimulation." (PMID 41295545, 2025). "For T cell-mediated immunity, IL-12 and IFNγ are key to controlling Mab infection and disease, and animal models consistently show an important role for CD4+ T cells in the lungs." (PMID 40415550, 2025). "Unstimulated IFNγ levels in blood remained at baseline during the pre-challenge period but increased by Day 15 post-infection (dpi) across all groups for generic PPD antigens." (PMID 41137142, 2025).
infection (continued). "The interferon-gamma release assay (IGRA) evaluates the infection status of M. tuberculosis by detecting interferon-gamma (IFN-γ) levels produced by T cells in response to stimulation with M. tuberculosis-specific antigens (such as ESAT-6 and CFP-10)." (PMID 41583454, 2025). "Th2- and eosinophil-expressed IL-4 increased sharply at late-phase time points after infection, peaking at 42 days and remaining elevated up to 70 days after infection, overwhelming local production of IL-17 and IFNγ." (PMID 41294879, 2025). "The release of IFNγ is essential for host defence against infection with intracellular microbes by regulating adaptive immune function and anti-microbial immune effector pathways by antigen presenting cells (APCs) and macrophages." (PMID 40939292, 2025). "RSV induced IFNα, the key Th1 factor IFNγ and several inflammatory cytokines suggesting that our cell culture model is suitable for investigating immune pathologies in infection defense mechanisms to RSV in COPD." (PMID 40506734, 2025). "This Breg expansion is associated with reduced IFNγ/IL10 ratio, reduced TNFα production and impaired activation of myeloid cells, likely compromising the innate response to infection." (PMID 41191641, 2025). "Initially, the immune response focused on combating the infection, evidenced by strong correlations among inflammatory cytokines like IL-1β, IL-6, IL-8, TNFα, and IFNγ." (PMID 40557167, 2025). "Comprehensive overview of research studies examining the role of IFN-γ (Interferon-gamma) and related immune pathways in macrophage responses to Mycobacterium tuberculosis (Mtb) and Mycobacterium leprae (M. leprae) infections." (PMID 41306590, 2025). "Compared with those in the WT infection group, the expression levels of common proinflammatory factors in the ΔL-lectin group were significantly lower, including IFNγ, IL1β, IL6, IL8, and TNFα." (PMID 40076391, 2025). "The functional mechanisms of bystander activation of T cells also involve the inflammatory cytokine IFNγ, which plays a crucial role early during infection by activating cytotoxic mediators in phagocytes, particularly macrophages." (PMID 41438743, 2025). "In subtype C, we found that the changes in the biomarker profiles post infection compared to pre-infection were due to increases in TNFα, IL-10, IL-6, IL-13, IL-5, IFNγ, IL-12, IL-4, ITAC, IL-17α, and IL-23." (PMID 40862133, 2025). "Next, we compared the ability of aged and infected neutrophils to repolarize LPS+IFNγ-treated MDMs and included direct infection with F. tularensis as an additional control." (PMID 40977725, 2025). "Another study in macaques showed that replication-competent SARS-CoV-2 was detectable in cultured BAL macrophages isolated 6 months after infection, inducing IFNγ and NK cell dysregulation." (PMID 40021627, 2025). "Infection was associated with the upregulation of proinflammatory genes CXCL10, IFNG, and IL15, alongside several NK and T cell activation markers such as CD244, CD40LG, and CD226." (PMID 39774119, 2025). "We found that these cells respond to infection by producing interferon gamma, a signaling protein that helps other immune cells control the parasite." (PMID 41452934, 2025). "Mice infected with RSV are euthanized at consecutive time points post-infection to collect samples and measure the number of inflammatory cells and levels of interferon-gamma (IFN-γ), nerve growth factor (NGF), and brain-derived neurotrophic factor (BDNF)." (PMID 40050867, 2025). "Clinical studies have consistently shown elevated IFNγ levels in the gastric mucosa of H. pylori-infected patients compared to uninfected individuals, a finding replicated in animal models of infection." (PMID 41573568, 2025). "Following a 1-h infection in naive or IFNγ-stimulated HFFs, the percentage of parasites that were extracellular vs. intracellular was determined." (PMID 40607979, 2025).
infection (continued). "Interferon-gamma (IFNγ) is a pleiotropic cytokine produced by natural killer (NK) cells during the early infection response." (PMID 39578552, 2025). "During an infection, C. trachomatis can encounter Trp starvation as a result of interferon-γ (IFNγ) binding to its receptor on the host cell, which activates the production of indoleamine 2,3-dioxygenase (IDO) that catabolizes Trp into N′-formylkynurenine." (PMID 39804088, 2025). "Regarding systemic immunity, natural infection and wP vaccination primarily induce T helper 1 (Th1) and Th17 cell-mediated immunity, leading to the secretion of interferon gamma and IL-17, respectively." (PMID 40709171, 2025). "In the case of co-stimulatory molecules, Cd40 and Cd86 were both upregulated by infection, with IFNγ further amplifying this effect." (PMID 40547518, 2025). "In this model, we observed that TVM and TMEM cells produced elevated levels of IFNγ at day 4 post-infection, in contrast to the nearly undetectable expression in TN cells." (PMID 41438743, 2025). "This molecule is typically activated by interferon-gamma (IFN-γ), a key player in defending the body against infections." (PMID 40627782, 2025). "In contrast, cytokine levels in spleen cells remained unchanged, except for an increase in IFNγ following intravenous infection." (PMID 40178612, 2025). "IFNγ transgene (SFV/IFNγ group) enhanced the effect of infection even more by reducing 51 genes and inducing 52 genes." (PMID 40547518, 2025). "The average number of parasites per vacuole was quantified 28 h post-infection in naive and IFNγ-stimulated HFFs." (PMID 40607979, 2025). "In agreement with our previous data, IFNγ production by CD4+ T cells significantly increased upon infection in both WT and TG mice." (PMID 40746561, 2025). "We found that the frequencies of IFNγ+ CD42+ cells were significantly elevated only in peritoneal cells from N. caninum-infected mice at 4 h post-infection." (PMID 39445806, 2024). "We found that TgPHYa overexpression has a dominant negative effect on IFNγ-controlled parasite virulence during the acute phase of the infection." (PMID 38857298, 2024). "S. Typhimurium infection of humanized mice resulted in elevated levels of the human TH1 cytokines IL-12 and IFNγ, whereas infection with ssrB mutant S. Typhimurium or S. Typhi elicited lower cytokine expression, with significantly lower levels of IL-12." (PMID 38497655, 2024). "Mechanistically, treatment with recombinant NPFF during infection reduced the frequency of IFNγ+ and ROS+ neutrophils but increased the proportion of CD204+ neutrophils and led to a decreased ability by NPFF-conditioned neutrophils to clear bacteria." (PMID 38295799, 2024). "Overall, these results show that IFNγ promotes C. albicans invasion into deep skin layers after intradermal infection and facilitates systemic fungal dissemination to kidneys." (PMID 39622833, 2024). "Mice were infected and bioluminescent imaging was performed throughout the infections, and serum IFNγ was analyzed 4 hpi by Luminex analysis (Data Set S1)." (PMID 39445806, 2024). "In advanced stages of infection, IFNγ is involved in the pathogenesis of several immunological disorders caused by unrestrained inflammatory responses." (PMID 38892353, 2024). "During the characterization of host IFNγ response to acute stages of T. gondii infection (tachyzoites), we discovered that IFNγ treatment of HFFs post infection with RH type I (RH) or type II (ME49) Δmyr1 translocon mutants led to early parasite egress." (PMID 39292011, 2024). "Distinct, cross-regulated populations of neutrophils were the primary source of NPFF and IFNγ during infection." (PMID 38295799, 2024). "(E) Quantification of Ct inclusion production during infection of unprimed and IFNγ-primed (100 U/mL) A549 cells at 24 hours post infection." (PMID 38358795, 2024). "This downregulation happens early in infection, priming cells to respond sub-optimally to IFNγ stimulation." (PMID 39194253, 2024).